PLCG2 (phospholipase C gamma 2)
Diseases named in the same sentence as PLCG2 in open-access papers (continued):
Sharing a sentence is not in itself a finding about the gene and the disease.
MALT lymphoma (2 papers, 2016 to 2021). An indolent, extranodal type of non-Hodgkin lymphoma composed of small B-lymphocytes (centrocyte-like cells). "The use of the Ali5 heterozygous point mutation, gain-of-function PLCγ2 mice in a model of Helicobacter felis infection showed PLCγ2 protects mice from developing gastric MALT lymphoma." (PMID 34157287, 2021). "Previously, our group found that phospholipase C gamma 2 (PLCG2) is overexpressed in MALT lymphoma tissue." (PMID 26966907, 2016). "This seemed likely, as Plcg2 activates NF-κB, a key molecule of MALT lymphoma development." (PMID 26966907, 2016).
marginal zone lymphoma (2 papers, 2021 to 2023). A usually indolent mature B-cell lymphoma, arising from the marginal zone of lymphoid tissues. "Some studies have shown that mutations in BTK and PLCG2 are the most common mechanisms of resistance to ibrutinib in CLL, WM, and marginal zone lymphoma (MZL)." (PMID 37048814, 2023). "Mutations in BTK at the binding site (BTKC481S mutation) or mutations in PLCG2, the kinase immediately downstream of BTK, are often seen in patients with CLL, MCL, WM, or marginal zone lymphoma (MZL) who developed resistance to ibrutinib." (PMID 35582375, 2021).
melanoma (2 papers, 2020 to 2024). A malignant, usually aggressive tumor composed of atypical, neoplastic melanocytes. "Firstly, we investigated the frequency and type of PLCG2 mutations in pan-cancer datasets, and the results showed that PLCG2 was most pronounced in melanoma, with a mutation frequency of more than 10%." (PMID 39494327, 2024).
myeloma (2 papers, 2019 to 2020). "Altogether, this suggests that due to anti-β2m antibodies, MHC-I locates to lipid rafts, activates Lyn and PLCγ2, which activate JNK and inhibit Akt and ERK pathways and finally induce myeloma cell apoptosis." (PMID 33384693, 2020). "Specifically, in malignant tumors, especially in myeloma, anti-MHC I antibody selectively induced tumor cell apoptosis, by activating Lyn and PLCγ2 to upregulate proapoptotic Bad and Bax expression." (PMID 31583257, 2019).
osteoporosis (2 papers, 2012 to 2022). A condition of reduced bone mass, with decreased cortical thickness and a decrease in the number and size of the trabeculae of cancellous bone (but normal chemical composition), resulting in increased fracture incidence. "Chrysanthemum morifolium water extract inhibits differentiation of bone marrow-derived macrophages by regulating PLCγ2/CREB/c-fos/NFATc1 signaling pathway, thereby alleviating osteoporosis." (PMID 36276853, 2022).
osteosarcoma (2 papers, 2016 to 2021). A usually aggressive malignant bone-forming mesenchymal neoplasm, predominantly affecting adolescents and young adults. "siRNA targeting Ezrin, a cytoplasmic peripheral protein involved in metastatic spreading of osteosarcoma and dependent on PIP2, also resulted in PLCγ2 upregulation in human osteosarcoma cell lines, while another study of osteosarcoma cell lines found PLCγ2 to be a differentially regulated gene." (PMID 34157287, 2021).
ovarian carcinoma (2 papers, 2022). A malignant neoplasm originating from the surface ovarian epithelium. "ISG15, SNCA, RIPK2, PLCG2, RHOU, TRIB2 and ELP2 influenced the OS and PFI of ovarian cancer patients in the TCGA-OV dataset, while RIPK2 also affected the OS and PFI of ovarian cancer patients treated with Taxol in the GSE30161, GSE32062 and GSE63885 datasets." (PMID 35477477, 2022). "Notably, bioinformatic analysis of publicly available ovarian cancer transcriptome datasets corroborates our hypothesis, by showing a favorable prognostic role of PLCG2 expression in advanced-stage HGSOC (data not shown)." (PMID 35120576, 2022).
periodontitis (2 papers, 2019 to 2024). An acute or chronic inflammatory process that affects the tissues that surround and support the teeth. "Studies have also shown that Btk can bind to key residues on PLCγ to activate PLCγ2; however, little is known regarding the potential role of Btk and PLCγ2 in apical periodontitis bone resorption." (PMID 31427888, 2019).
primary immunodeficiency (2 papers, 2018 to 2023). "The APLAID syndrome is a rare primary immunodeficiency caused by gain-of-function mutations in the PLCG2 gene." (PMID 36776842, 2023).
prostate carcinoma (2 papers, 2023 to 2024). A carcinoma that arises from epithelial cells of the prostate gland. "However, some OSRE genes, like JAK2 and PLCG2, were shared across liver, lung, and prostate cancers." (PMID 39594421, 2024).
rheumatoid arthritis (2 papers, 2021 to 2023). A chronic, systemic autoimmune disorder characterized by inflammation in the synovial membranes and articular surfaces. "PLCγ2 also appears to play a role in the chronic inflammatory disorder, rheumatoid arthritis (RA), as evident by an upregulation of the PLCγ2 gene signature of patient peripheral blood mononuclear cells." (PMID 34157287, 2021).
serous ovarian cancer (2 papers, 2022 to 2024). "In BRCA wild-type high-grade serous ovarian cancer, PLCG2 might be a potent biomarker for predicting the response of patients to first-line chemotherapy." (PMID 39494327, 2024).
thromboembolic diseases (2 papers, 2020 to 2022). "In conclusion, we propose a novel inhibitory pathway of NF-κB-mediated PLCγ2-PKC activation by auraptene in human platelets, and further supported that auraptene possesses potent activity for thromboembolic diseases." (PMID 32646046, 2020). "Herein, we propose a novel inhibitory pathway of NF-κB-mediated PLCγ2-PKC activation by auraptene in human platelets, and further supported that auraptene possesses potent activity for clinical therapeutic or prophylactic application for treatment with thromboembolic diseases." (PMID 32646046, 2020).
allergic rhinitis (1 paper, 2025). Inflammation of the nasal mucous membranes caused by an IgE-mediated response to external allergens. "Allergic rhinitis was reported in 1.8% of patients (mostly those with PLCG2 deficiency)." (PMID 41142799, 2025).
Anxiety (1 paper, 2025). Intense feelings of nervousness, tension, or panic often arise in response to interpersonal stresses. "Together, these findings suggest that the PLCγ2-P522R variant promotes an anxiety phenotype in APP/PS1 mice, which may promote longevity via protection against environmental threats through mechanisms associated with altered microglial functions." (PMID 40038760, 2025). "Moreover, the PLCγ2-P522R variant promoted anxiety in these mice." (PMID 40038760, 2025). "This interpretation is supported by direct evidence of increased anxiety in PLCγ2-P522R mice." (PMID 40038760, 2025). "The tendency of PLCγ2-P522R mice to rush into the dark despite having mild foot shock a day earlier can stem from changes in four CNS systems that regulate 1) the pain threshold, 2) spontaneous motor activity, 3) memory, and 4) the level of anxiety." (PMID 40038760, 2025).
apical periodontitis (1 paper, 2019). "Cells positive for Btk, PLCγ2, and NFATc-1 were stained dark brown as shown by immunohistochemistry and were expressed in apical periodontitis at 0 to 4 weeks in experimental mice." (PMID 31427888, 2019). "The mechanism of Btk-PLCγ2 in apical periodontitis bone destruction was further examined by cell interference to inhibit or enhance the expression of Btk in osteoclasts." (PMID 31427888, 2019). "Therefore, this study verified the role of Btk and PLCγ2 in bone resorption of apical periodontitis by in vivo and in vitro experiments." (PMID 31427888, 2019). "Studies have shown that the Bruton tyrosine kinase- (Btk-) phospholipase Cγ2 (PLCγ2) signaling pathway plays an important role in bone absorption, but it is unknown whether it plays a role in apical periodontitis bone destruction." (PMID 31427888, 2019). "It was found that the expression of Btk, PLCγ2, and NFATc-1 changed significantly with the progression of inflammation and bone destruction, indicating that Btk and PLCγ2 may be involved in the progression of inflammation in apical periodontitis and bone absorption." (PMID 31427888, 2019).
asthma (1 paper, 2021). "Subsequent whole-exome sequencing analyses revealed that the phospholipase C gamma 2 (PLCG2) gene, located in that region, was enriched of deleterious variants among asthma cases." (PMID 34203440, 2021).
atherosclerosis (1 paper, 2023). A disease characterized by the build-up of fatty material and calcium deposition in the arterial wall resulting in partial or complete occlusion of the arterial lumen. "Additional GWAS hits in the shared cross-species CAD/atherosclerosis subnetworks were peripheral nodes (e.g. CETP, PLCG2, BASP1, MSR1, ST5, ASAP2)." (PMID 38060277, 2023).
autism (1 paper, 2022). Persistent deficits in social interaction and communication and interaction as well as a markedly restricted repertoire of activity and interest as well as repetitive patterns of behavior. "We found that Sgce and Plcg2 were the 2nd and 8th most downregulated transcripts, and Nlrc4 the 6th most upregulated transcript in microglia derived from control and LPS-treated mice upon an analysis of a subset of 148 autism and pediatric immune disorder genes." (PMID 35773312, 2022).
Azoospermia (1 paper, 2016). Absence of any measurable level of sperm,whereby spermatozoa cannot be observed even after centrifugation of the semen pellet. "Using this line, we examined whether epididymal epithelial cell-specific reactivation of PLCγ2 could rescue PLCγ2-deficient mice from impaired lumen expansion and azoospermia." (PMID 26950550, 2016). "In our previous study of the vascular phenotype, we found that PLCγ2-deficient males, but not females, are infertile, owing to azoospermia." (PMID 26950550, 2016).
bronchiectasis (1 paper, 2023). Segmental, irreversible dilation of the bronchial tree resulting in the accumulation of secretions which leads to obstruction. "Participant 2 has a compound heterozygous p.Leu845_Leu848 deletion in PLCG2 and clinically suffered from skin rash and recurrent lung bacterial infections leading to bronchiectasis and acute episodes of hemoptysis requiring partial pneumonectomy." (PMID 36997670, 2023).
cervical cancer (1 paper, 2012). A primary or metastatic malignant neoplasm involving the cervix. "Therefore, pre-clinical study in animal models of cervical cancer should be carried out through tumor-targeted delivery of anti-PLCG2 or CALM1 siRNA in combination with passively diffusible anti-cancer drugs." (PMID 22709569, 2012). "PLCG2 and CALM1 of Ca2+-calmodulin signalling pathways are the two potential targets for gene knockdown in doxorubicin and paclitaxel-based chemotherapy of cervical cancer." (PMID 22709569, 2012). "Thus, PLCG2 and CALM1 genes are two potential targets for gene knockdown in doxorubicin and paclitaxel-based chemotherapy of cervical cancer." (PMID 22709569, 2012).
chronic myeloid leukemia (1 paper, 2019). "In another example, GAB2 has a regulatory role for PLCG2 in the osteoclast differentiation pathway, as well as an activating role in the chronic myeloid leukemia pathway." (PMID 31706268, 2019).
deficiency (1 paper, 2025). "We describe a case of early-onset bibasilar emphysema in an individual with frequent respiratory infections and immunoglobulin deficiencies, found to have a PLCG2 mutation on genetic testing." (PMID 41537131, 2025). "Testing for alpha-1 antitrypsin deficiency and cystic fibrosis was negative, prompting genetic testing, which revealed the PLCG2 Met1141Lys variant of uncertain significance." (PMID 41537131, 2025).
emphysema (1 paper, 2025). "•Early-onset emphysema as a novel phenotype of PLCG2 mutation." (PMID 41537131, 2025). "Mechanistically, PLCG2 mutations could contribute to emphysema through recurrent infections, leading to chronic inflammation and lung parenchymal damage." (PMID 41537131, 2025). "Here, we present a case of a non-smoking patient with early-onset emphysema and immunoglobulin deficiency, subsequently found to carry the PLCG2 Met1141Lys variant." (PMID 41537131, 2025). "In a cohort of 76 patients with PLCG2 variants, emphysema was not reported as a phenotype of PLAID/APLAID disorders." (PMID 41537131, 2025).
esophageal adenocarcinoma (1 paper, 2021). A malignant tumor with glandular differentiation arising predominantly from Barrett mucosa in the lower third of the esophagus. "PLCγ2 was also found to potentially contribute to other tumorogenic situations such as the formation of esophageal adenocarcinoma." (PMID 34157287, 2021).
HIV-1 infection (1 paper, 2025). The type species of lentivirus and the etiologic agent of acquired immunodeficiency syndrome (AIDS). "Phospholipase C, gamma-2 (PLCG2) was downregulated and tumor necrosis factor receptor superfamily member 1B (TNFRSF1B) was upregulated in vaccinated animals and enriched in HIV-1 infection." (PMID 41036542, 2025).
Hodgkins lymphoma (1 paper, 2021). A heterogeneous group of malignant lymphoid neoplasms of B-cell origin characterized histologically by the presence of Hodgkin and Reed-Sternberg (HRS) cells in the vast majority of cases. "Downregulation of PLCγ2 gene pathways, and other BCR-related genes, along with EBV infection, is also associated with Hodgkin’s lymphoma." (PMID 34157287, 2021).
Hyperglycemia (1 paper, 2025). An increased concentration of glucose in the blood. "In diabetic wounds, chronic hyperglycemia leads to epigenetic dysregulation, including hypermethylation of the phospholipase C gamma 2 gene (PLCγ2) promoter, which suppresses PLCγ2 expression and impairs angiogenic responses." (PMID 40606909, 2025).
Hyperinsulinemia (1 paper, 2021). An increased concentration of insulin in the blood. "Downregulation of PLCG2 led to decreased cellular viability and proliferation in an in vitro model, and therefore it is likely that a hyperinsulinemia-mediated PLCG2 upregulation promoted cell proliferation." (PMID 33690729, 2021).
hypophosphatemia (1 paper, 2011). Lower than normal levels of phosphates in the circulating blood.
ischemic disease (1 paper, 2022). Lack of blood supply to an area of the body, resulting in impairment of tissue oxygenation. "It is possible that Csf1r/Plcg2 exerted the similar effects in MI that is also an ischemic disease." (PMID 35346355, 2022).
lymphoproliferative disorders (1 paper, 2014). "In fact, our discovery may be of fundamental biological significance as PLCγ2 is a critical signaling regulator of B-cell activation, whose hypoactivation could be used as a biomarker for response to therapies targeting the BCR signaling pathway, in CLL and other lymphoproliferative disorders." (PMID 24489640, 2014).
male infertility (1 paper, 2016). The inability of the male to effect fertilization of an ovum after a specified period of unprotected intercourse. "Phospholipase Cγ2 (PLCγ2)-deficient mice exhibit misconnections of blood and lymphatic vessels, and male infertility." (PMID 26950550, 2016). "We found that PLCγ2 expression in the epididymal duct is restricted to clear cells and PLCγ2 deficiency in these cells leads to male infertility." (PMID 26950550, 2016). "However, the pathogenesis of male infertility in PLCγ2-deficient mice is not clear, and it is not known whether male infertility is a secondary defect related to the vascular defect or not." (PMID 26950550, 2016).
myocarditis (1 paper, 2023). Myocarditis is a condition that is characterized by inflammation of the heart muscle (myocardium). "Given that PLCG2 is involved in multiple immune responses, its high expression may promote inflammation leading to myocarditis." (PMID 37109540, 2023).
Obesity (1 paper, 2020). Accumulation of substantial excess body fat. "Obesity group also showed a lower mutation frequency of PLCG2, STK31, ADGB, and so on." (PMID 33197880, 2020).
oral squamous cell carcinoma (1 paper, 2024). "Briefly, phospholipase C gamma 2 (PLCG2), which is related to oral squamous cell carcinoma (OSCC) clinical stage and overall survival, was affected by the circRNA-1269a/miR-1269a axis." (PMID 38539573, 2024).
osteopetrosis (1 paper, 2025). Osteopetrosis, also known as marble bone disease, is a descriptive term that refers to a group of rare, heritable disorders of the skeleton characterized by increased bone density on radiographs. "The absence of PLCγ2 in mice leads to osteopetrosis because of defective osteoclastogenesis." (PMID 39894822, 2025).
postmenopausal osteoporosis (1 paper, 2012). Metabolic disorder associated with fractures of the femoral neck, vertebrae, and distal forearm. "Because osteoclast-mediated bone resorption contributes to postmenopausal osteoporosis, we hypothesized that PLCγ2 may also play a role in oestrogen deficiency–induced bone loss." (PMID 21749368, 2012).
Pyoderma (1 paper, 2021). Any manifestation of a skin disease associated with the production of pus. "Here we report a rare case of APLAID patient carrying a novel heterozygous missense PLCG2 I169V mutation with gangrenous pyoderma and concomitant high serum immunoglobulin (Ig) E level." (PMID 34093563, 2021). "Here, we report the first case of a Chinese patient with APLAID caused by a novel PLCG2 gene mutation with rare manifestation of gangrenous pyoderma and concomitant high serum immunoglobulin (Ig) E level, which has not been reported before." (PMID 34093563, 2021). "Our study reported the first case of APLAID with gangrenous pyoderma and concomitant high IgE carrying a novel PLCG2 mutation, which may expand the clinical phenotype and genotype of APLAID." (PMID 34093563, 2021).
sarcoma (1 paper, 2023). A usually aggressive malignant neoplasm of the soft tissue or bone. "Within the circuit, the isoform PLCγ2, linked to the activation of WASPs, is positively correlated with good patient prognosis, and, in sarcoma, it promotes the infiltration of anti-tumor M1 macrophages, T cells, and monocytes into the TME." (PMID 37834179, 2023).
scleroderma (1 paper, 2023). Scleroderma is a rare autoimmune connective tissue disorder characterized by abnormal hardening of the skin and, sometimes, other organs. "Genes associated with ECM components, such as COL4A1, heparan sulfate proteoglycan 2 (HSPG2), and actin beta (ACTB), as well as phospholipase C gamma 2 (PLCG2), fatty binding protein 4 (FABP4), and galectin 1 (LGALS1), also showed higher expression levels in scleroderma." (PMID 37443817, 2023). "PLCG2, FABP4, and LGALS1, which are involved in inflammatory pathways as well as pathways regarding leukocyte transendothelial migration, vascular smooth muscle contraction, and the pro-inflammatory PPAR signalling pathways that were upregulated were also upregulated in scleroderma ECs." (PMID 37443817, 2023).
Sepsis (1 paper, 2024). Sepsis is defined as life-threatening organ dysfunction caused by a dysregulated host response to infection. "For sepsis, we found that PLCG2 was upregulated in immune cells during sepsis compared to healthy individuals, BCL6 was upregulated in Pre-B cells (CD34−) during sepsis, and IGF2BP2 was upregulated in GMP cells." (PMID 38167131, 2024).
skin inflammation (1 paper, 2025). "Mice lacking Plcg2 demonstrated resistance to IgE-mediated skin inflammatory responses, highlighting the crucial role of Plcg2 in FcεR-mediated skin inflammation." (PMID 40322063, 2025).
ST Elevation Myocardial Infarction (1 paper, 2019). A myocardial infarction that produces elevation in the ST segments of the ECG. "We chose PLCγ2 as a key protein in GPVI signalling that we previously observed to be altered following CRP-XL stimulation in platelets from ST-elevation myocardial infarction (STEMI) patients." (PMID 30658193, 2019).